CD4 (CD4 molecule)
Diseases named in the same sentence as CD4 in open-access papers (continued):
Sharing a sentence is not in itself a finding about the gene and the disease.
infection (continued). "First, in agreement with our previous reports, our model of functional cure for HIV infection demonstrates that acute mucosal CD4+ T cell depletion has no prognostic value for the chronic outcome of infection." (PMID 21829366, 2011). "The Eps15-DN suppressed the CD4-independent mNDK infection, but not the CD4-dependent infection under conditions that the levels of Eps15-DN expression in the CD4-negative and –positive cells were similar." (PMID 21541353, 2011). "The primary difference between the two virus infections is that H310A1 infection activates CD4+CD25+FoxP3+ Treg cells which are absent in H3 infected mice." (PMID 21255407, 2011). "HIV/TB coinfected persons have been shown to have a higher mortality rate than those without either infection alone, regardless of CD4 count." (PMID 21234380, 2011). "Of course, our data do not rule out a protective role for CD4+ T cells in combination with antibody production after vaccination or during a secondary infection." (PMID 21663697, 2011). "Infection with the human immunodeficiency virus type 1 (HIV-1) requires attachment to one of the principal chemokine coreceptors, namely CCR5 and CXCR4 for effective entry into CD4+ T-cells." (PMID 21789236, 2011). "Adoptive transfer of LCMV-immune CD4+ T cells to CD8-depleted BL/6 mice did not reduce the viral load in spleen or liver on day 11 after infection." (PMID 21966366, 2011). "A high force of infection results in exogenous primary and secondary TB infections, which will rapidly progress to clinical disease, particularly in HIV-infected individuals with low CD4 cell counts." (PMID 21999773, 2011). "By contrast, the N197S change, which increases coreceptor-binding site exposure and enhances CD4-independent infection, exerted a slightly negative effect on cold sensitivity." (PMID 21731494, 2011). "Authors suggested that the vast majority of bystander cell death in these tissues involved abortive HIV infection: naïve CD4+ T cells are refractory to productive HIV infection; after viral entry, infection is aborted as reverse transcription is initiated but fails to reach completion." (PMID 21994747, 2011). "Without APS stimulation, the TLR4 expression on CD4+CD25+Tregs isolated from burn plus infection mice were significantly increased on PBD7." (PMID 21698274, 2011). "At the time point of infection, frequencies of CD4 T cells were comparable in all experimental groups harboring CD4 T cells (data not shown)." (PMID 21901102, 2011). "We report here that partial Treg cell depletion prior to FIV infection does not significantly change provirus, viremia, or CD4+ T cell levels in blood and lymphoid tissues during the acute phase of disease." (PMID 21364928, 2011). "This is in agreement with studies in mice where the absence of CD4+ T cells in primary infection limits the subsequent ability of CD8+ T cells to respond to secondary infection." (PMID 21359149, 2011). "It is clear from recent investigations that the Th1/Th2 paradigm must be expanded to include the newly identified CD4 and CD8 T cells subsets that comprise the effector and regulatory subsets responding to mycobacterial antigens during different stages of infection." (PMID 21197095, 2011). "The endosome acdification inhibitor (chloroquine) and endocytosis inhibitor (dynasore) suppressed the CD4-independent ROD/B infection, but not the CD4-dependent infection." (PMID 21541353, 2011). "Indeed, Nef can restrict superinfection via downregulation of CD4, CCR5 and CXCR4 during productive infections." (PMID 21722380, 2011). "Any effect of enhancing infection by increasing the affinity of the envelope protein for CD4 should be reduced in a strain that does not have an absolute requirement for binding to CD4." (PMID 22163292, 2011). "Cystatin C neither inhibited cathepsin B activity nor enhanced the CD4-independent vector infection in 293T cells, probably because the cathepsin B activity of 293T cells was originally low." (PMID 21541353, 2011).
infection (continued). "HTLV-1 is associated with an increased CD4 count, also in HIV-2 infection, but this does not seem to result in a better outcome of the infection." (PMID 22194980, 2011). "Both LCMV-specific CD8 T cells and CD4 T cells upregulated RANTES mRNA expression, with a high amount of RANTES mRNA maintained in LCMV-specific CD8 T cells past day 30 following LCMV Armstrong or clone 13 infection." (PMID 21814510, 2011). "Our results show, however, that in the absence of the relevant TLRs, i.e. TLR2 and TLR4, CD4+ T-cells can be sensitized to release IFNγ upon infection with C. pneumoniae." (PMID 22096480, 2011). "In contrast, the inhibitors less efficiently attenuated the CD4-dependent HIV-1 vector infection than the CD4-independent infection, as they did in a previous report, suggesting that the CD4-dependent infection does not occur through acidic endosomes." (PMID 21541353, 2011). "CD3+ and CD4+ but not CD8+ counts were lower for those born during the hungry/high infection season." (PMID 21676219, 2011). "The cathepsin L specific inhibitor, CLIK148, did not affect the mNDK vector infection in CD4-negative and –positive cells (data not shown)." (PMID 21541353, 2011). "Together, our results suggest that initial development of the L. mexicana lesion is dependent on an IL-4/13-responsive non-T cell population, whilst progressive infection is dependent on CD4+ T cells responsive to IL-4." (PMID 21245915, 2011). "The cathepsin B overexpression significantly inhibited the CD4-independent vector infection, but did not the CD4-dependent infection." (PMID 21541353, 2011). "Collectively, these findings indicate that cystatin C enhances the CD4-independent mNDK vector infection in HeLa and TE671 cells, but does not in 293T cells." (PMID 21541353, 2011). "We observed CD4+CD25+CD127low T cells in both PB and LN of RM during early infection." (PMID 21483689, 2011). "We observed characteristic CD4+ and CD8+ T cell dynamics during acute FIV-C36 infection." (PMID 21364928, 2011). "Inhibitors of endosome acidification or endocytosis significantly attenuated the CD4-independent HIV-1 vector infection, but not the CD4-dependent infection, as expected." (PMID 21541353, 2011). "HRM scores for adults with non-recent infection who had CD4 cell counts above vs. below 50 cells/mm3 were not significantly different for five of the six regions analyzed." (PMID 22073290, 2011). "As seen in the mNDK infection, the ROD/B infection was enhanced by CA-074Me treatment at 50 μM in CD4-negative TE671 cells." (PMID 21541353, 2011). "With samples from IgG+ individuals and from three survivors of ZEBOV infection, the percentage of circulating CD4+ T cells producing IFN-γ did not increase after PBMC stimulation (data not shown)." (PMID 20161740, 2010). "Upon infection with Ye, IL-12 as well as TNF production was induced in CD4+ and CD4−CD8α−, but decreased in CD8α+ DCs, which in turn may account for reduced T-cell priming by CD8α+ DCs." (PMID 21124820, 2010). "There were also no detectable differences in viral loads or CD4 counts following treatment interruption between the two arms when separately analyzed by initial treatment during acute vs. early infection (data not shown)." (PMID 20479938, 2010). "We observed that there was no significant decrease in cell-free infection of inhibitor-treated Raji/CD4 target cells with HTLV-1 and HIV-1 VLPs (data not shown)." (PMID 20195464, 2010). "Of the Th lymphocytes, the only statistically significant change was the decrease in number of CD4 lymphocytes observed after the infection with the SPI2o mutant when compared with the non-infected mice." (PMID 20226037, 2010). "Glycosylation in V1V2 was increased in those with stage 3 (β = 0.96, p = 0.002), but not stage 2 or 4 compared to stage 1 infection, and was decreased in those with CD4 counts <200 cells/ml (β = −0.63, p = 0.04 compared to CD4 counts >500)." (PMID 21187897, 2010).
infection (continued). "In addition to the CD4/CCR5 mediated entry of HIV-1 into the cell by membrane fusion, an alternative route of infection has been described in Mφ that involves the uptake of the virus via macropinocytosis." (PMID 20374633, 2010). "Baseline median CD4 counts were similar between those with infection at follow-up and those without (489 vs. 474, p = 0.99), as were baseline median log10 HIV RNA levels (5.1 log10 vs 4.9 log10 HIV RNA, p = 0.29)." (PMID 20361031, 2010). "Qa-1 knockout mice had increased CD4+ T-cell responses upon infection and vaccination, due to the lack of Qa-1 restricted CD8+ Tregs." (PMID 20195504, 2010). "Together, these data indicate that the degree of HIV-specific CD8+ T-cell perforin expression is predictive of the ability to control viral load independent of the rate of CD4+ T-cell decline, progression status, or infection duration." (PMID 20523897, 2010). "Induction of an immunological synapse (IS) between Jurkat effector cells and Raji/CD4 target cells does not increase infection with either HIV-1 or HTLV-1 VLPs suggesting that cell-to-cell infection requires the formation of specialized VS." (PMID 20195464, 2010). "Unlike the response to schistosome eggs, the CD4+ T cell responses induced by schistosome worms, especially during normal permissive infection, have not been extensively characterized." (PMID 21078176, 2010). "To explore these issues, we tested the capacity of Gag-specific memory CD4+ T cell to differentiate in vitro, comparing primary CD4+ T cell lines derived from HIV controllers and efficiently treated patients with equivalent duration of infection." (PMID 20195518, 2010). "It is notable that the degree of depletion in SM gut CD4+ T cells exceeds the proportion that express detectable CCR5, and it will be important to determine if this is due to infection and targeting of CCR5-negative cells in wild-type animals mediated by other coreceptors." (PMID 20865163, 2010). "There was no statistical difference in the distribution of naïve, as well as CD62L+ and CD62L− I-AbGP67-77 tetramer+ CD4+ T cells within the lung, spleen and lymph nodes 45 days post-infection with LCMV-ARM (data not shown)." (PMID 20369005, 2010). "The CDC has defined this entity as sustained CD4+ Lymphocytopenia (less than 300 CD4+ lymphocytes per micro liter) with persistent T4 lymphocytopenia following treatment (or resolution of infection) without immunosuppression in HIV negative individuals." (PMID 20806085, 2010). "Anti-HTLV-1 human serum or anti-CD4 mAb were titrated to give greater than 95% inhibition of infection; control serum or mAb did not inhibit Luc transduction and neutralization of infection was specific for each virus." (PMID 20195464, 2010). "Similarly, in an alternative approach that utilizes CD4+/CCR5+ T cells, the NOMI reporter cell line as target, CM inhibited trans infection of reference viruses and two of the transmitted viruses (WITO and CHO58)." (PMID 21179465, 2010). "For primary infections, these studies have demonstrated an essential role of innate and adaptive immunity, including TLR9 mediated recognition by DC, the complement system, NK cells, type I and II IFNs, B cells, CD4 T cells and CD8 T cells." (PMID 20300179, 2010). "In addition, opsonization of HIV-1 with complement modulates in vitro the infection of epithelial and dendritic cells, as well as the transfer of HIV-1 from dendritic cells to CD4 T cells." (PMID 20546571, 2010). "First, they mediate transfer of infection to CD4+ T cells, particularly to the antigen-specific CD4+ T cells with which they interact, thus simultaneously driving virus amplification and impairment of the HIV-specific CD4+ T cell response." (PMID 20937128, 2010). "Following a genital tract primary infection, nu/nu mice responded with IL-10 mRNA expression levels in the LGT of comparable magnitude irrespective of if the CD4+ T cells were IL-10-deficient or normal." (PMID 21079691, 2010).
infection (continued). "The DC activation statusafter infection was evaluated by assessing the expression of the co-stimulatory molecules CD80 and CD86, as well as by their capacity to present MHC class I and II restricted epitopes to OVA-specific CD8+ or CD4+ T cells, respectively." (PMID 20628596, 2010). "CD25 and CD69 expression on CD4+ and CD8+ T cells each peaked between weeks 3 and 4 post-infection." (PMID 20714351, 2010). "This preferential infection was evident in both CD8+ T cells and CD4+ T cells." (PMID 21994688, 2010). "Thus, HeLa cells expressing low CD4 but high CCR5 (RC49 cell line) were infected with Env-pseudotyped viruses and the degree of infection was obtained by measuring the intracellular p24." (PMID 20860805, 2010). "CD4+ and CD4−CD8α− DCs showed similar OVA degradation as PBS-treated mice 24 h post infection." (PMID 21124820, 2010). "Therefore, we isolated splenocytes before and 10 days after infection of mice with E. muris, and IFN-γ production in gated splenic CD4 T cells was analyzed by flow cytometry." (PMID 20668698, 2010). "Results suggest that CD4+ cells are the major contributors to IL-17A production in infected LVS lungs, yet γδ T cells may have a role in the initial phase of infection." (PMID 20585449, 2010). "Despite these observations, identifying the functional importance of Tregs during in vivo infection has been limited, in part, by the lack of unique markers that allow their discrimination from other CD4+ T cell subsets." (PMID 20714351, 2010). "The capacity of R5 envelopes to confer infection of macrophages correlated with their sensitivity to inhibitors that blocked envelope: CD4 interactions, but not with those targeting envelope:CCR5 interactions or gp41 conformational changes." (PMID 20507591, 2010). "In both primary CD4+ T cells and P2 cells, approximately 50-60% of cells showed polarized morphology, and infection with VSV-G-pseudotyped HIV-1 did not substantially alter the percentage of polarized cells." (PMID 21060818, 2010). "The divergent mDC response contrasted with changes in CD4+ T cells, which did not statistically differ between groups at any time before or after infection." (PMID 21203477, 2010). "Using this approach, we have determined the molecular structures of several SIV and HIV-1 strains, including an SIV strain that does not require cell surface receptor CD4 for entry and infection." (PMID 21203482, 2010). "The data demonstrate that SIVmne027 is the dominant virus regardless of the route of infection, indicating that the capacity to replicate efficiently in CD4+ T cells is important for fitness." (PMID 20942954, 2010). "There was no statistical correlation between the absolute numbers of mDC with CD4+ T cells counts during infection, nor was this correlated with pDC." (PMID 21118577, 2010). "Despite a strong immune response resulting in decreasing viral load and increasing numbers of circulating virus-specific CD4+ T cells following the acute phase, the host is not capable of clearing the infection." (PMID 20569472, 2010). "Hence, the functional relevance of Env (and Gag) specific CD4+ and CD8+ T cells in setting of vaccination for prevention of infection needs to be further explored." (PMID 21085591, 2010). "The cell proliferation marker was found on 80% of intestinal CD4+ cells four weeks after infection, as opposed to on less than 10% in healthy patients." (PMID 20875154, 2010). "Interestingly, after infection of mice with viruses such as respiratory syncytial virus and lymphocytic choriomeningitis virus, the expression of asialo-GM1 increases on both CD4+ and CD8+ cells." (PMID 20657846, 2010). "Mice lacking CD4 cells (Cd40-/- and class II-/- mice), however, recovered from infection similar to wild type mice." (PMID 20667098, 2010). "The decline of CD4+T cells at the acute stage of infection (week 2-4 pi) was slightly more pronounce in non-DMPA macaques than the DMPA-treated macaques." (PMID 19891783, 2009).
infection (continued). "Unlike clade B infection, in which Gag and Nef CD4+ T cell responses dominated, we noted a restriction of CD4+ T cell responses to the Gag protein." (PMID 19352428, 2009). "At least two fundamental characteristics of SIV infection of natural host species that appear to distinguish them from pathogenic infections include the lack of chronic immune activation and the paucity of CCR5+ CD4+ target cells." (PMID 20011508, 2009). "We found that, two weeks post infection, there was a small and non-significant increase in the frequency of proliferating CD4+ T cells in the draining lymph nodes of healer mice compared with nonhealer mice (1.05±0.2% vs 0.76±0.2%, P>0.05)." (PMID 19597544, 2009). "These are common kinetics of free EBs and CD4+ T cell activity during a second infection in the absence of antibody." (PMID 19727394, 2009). "Together, these results suggest that DC-SIGN, DC-SIGN-NR, Mannan receptors, CD4 or the HIV-1 co-receptors are not involved in T cell mediated infection of DC." (PMID 19829715, 2009). "We found that there was a small decrease in the frequency of proliferating CD4+ T cells in the draining lymph nodes of nonhealer mice compared with healer mice 2 weeks post-infection (2·65 ± 0·26% vs. 3·50 ± 0·36%, P < 0·05)." (PMID 19292771, 2009). "The negligible infection of mDC confirms that the pDC result was not due to contaminating CD4+ T cells, as mDC and pDC were sorted simultaneously from the same tubes." (PMID 19424421, 2009). "Tissue macrophages are infected primarily through the CCR5 coreceptor, and individuals that lack CCR5 are highly resistant to infection, irrespective of CD4+ T cell infection." (PMID 19674458, 2009). "Supporting an alternative infection hypothesis, Bomsel showed that HIV-1 entered through the epithelial barrier and was transmitted to submucosal DCs and CD4+ T cells by transcytosis." (PMID 19180188, 2009). "Second an efficient but transient primary immune response, leading to partial control of the infection, but ultimately CD4 memory cells are absent while CD8 memory cells are present at a variable level, leading to chronic infection." (PMID 21994550, 2009). "HIV-1 is capable of directly infecting different DC subtypes (known as cis infection), but at a lower efficiency than HIV-1's ability to infect activated CD4+ T cells; therefore, only a small percentage of circulating DCs are positive for HIV in infected individuals." (PMID 19486514, 2009). "Incubation of the viruses at 37°C for increasing time periods in the absence of sCD4, followed by infection of CD4+CCR5+ cells, revealed a gradual reduction of infectivity, with half-lives ranging from 6.9 to 12.1 hours." (PMID 19343205, 2009). "Both sCD4 and JRC-II-191 efficiently activated the envelope glycoproteins to mediate infection of cells lacking CD4, in a manner dependent on coreceptor affinity and density." (PMID 19343205, 2009). "We could observe a progressive sequestration of both CD4+ and CD8+ T cells starting 3 days post-infection in both mouse strains." (PMID 19547708, 2009). "In order to evaluate whether the two infections also have similar levels of pDC depletion in early and advanced HIV disease, we stratified the HIV-1 and HIV-2 cohorts according to CD4 T cell counts (>350 and <350 CD4 T cells/μl)." (PMID 19936055, 2009). "This leads us to conclude that elements of the T cell response, likely including IFN-γ production by CD4 and CD8 T cells, can control certain features of the infection that make significant contributions to its lethality but that antibody is required for virus clearance." (PMID 19806203, 2009). "Both CD4+ and CD8+ T cells from C57BL/6 mice up-regulated CXCR3 expression levels during infection." (PMID 19343215, 2009).